CFTR (CF transmembrane conductance regulator)
Diseases named in the same sentence as CFTR in open-access papers (continued):
Sharing a sentence is not in itself a finding about the gene and the disease.
cystic fibrosis (continued). "Cystic fibrosis is a chronic disorder caused by autosomal-recessive mutations in the cystic fibrosis transmembrane conductance regulator (CFTR) gene." (PMID 33298147, 2020). "Cystic fibrosis is an inherited disease caused by mutations in the cystic fibrosis transmembrane conductance regulator (CFTR) gene." (PMID 33036232, 2020). "Cystic fibrosis is caused by mutations in the gene encoding the Cystic Fibrosis Transmembrane conductance Regulator (CFTR) channel important for mucus hydration." (PMID 32547962, 2020). "Cells marked by cystic fibrosis transmembrane conductance regulator (CFTR) were identified in the lungs of human and mouse and were able to regulate luminal pH that was implicated in the pathogenesis of cystic fibrosis." (PMID 33287869, 2020). "Cystic fibrosis is an autosomal recessive life-limiting disorder due to mutations of the gene encoding the cystic fibrosis transmembrane conductance regulator (CFTR)." (PMID 32326546, 2020). "The CFTR gene has been identified as a causative gene of cystic fibrosis, and it is also reported to be a gene associated with pancreatitis." (PMID 33375361, 2020). "Cystic fibrosis patients develop a severe form of the disease when the cystic fibrosis transmembrane conductance regulator (CFTR) gene is affected by nonsense mutations." (PMID 32899265, 2020). "SLC6A14 has been also proposed to modify the phenotype of cystic fibrosis – a fatal genetic disorder caused by mutations in the Cystic Fibrosis Transmembrane Conductance Regulator (CFTR) gene." (PMID 33195271, 2020). "Since most studies investigating to role of CFTR in inflammation focus on mutated CFTR and cystic fibrosis, the data available from settings with wild-type CFTR are sparse." (PMID 33250777, 2020). "CFTR favors epithelial surface hydration prominently in the lung airways and pancreas, and its dysfunction is implicated in cystic fibrosis." (PMID 32392767, 2020). "Cystic fibrosis is caused by mutations in the gene encoding the cystic fibrosis transmembrane conductance regulator (CFTR)." (PMID 32326361, 2020). "The development of an efficient technique for correction of p.F508del mutation in the CFTR gene would be a major breakthrough in the treatment of cystic fibrosis." (PMID 33175893, 2020). "A proof-of-concept clinical example is the identification of a drug with the intestinal organoids derived from a cystic fibrosis patient carrying a rare CFTR mutation, and the drug named Kalydeco was shown to be effective." (PMID 32588198, 2020). "In a search for related articles, no relevant studies on kidney diseases were identified, and most reports were associated with cystic fibrosis, which is caused by pathogenic variants in CFTR." (PMID 32363171, 2020). "Excessive activation results in intestinal fluid loss during secretory diarrheas, whereas CFTR mutations underlie cystic fibrosis." (PMID 32934006, 2020). "Cystic fibrosis is a severe autosomal recessive disease due to mutations in the cystic fibrosis transmembrane regulator (CFTR) gene." (PMID 32242045, 2020). "Inherited defects in the CFTR gene cause cystic fibrosis, an autosomal recessive disease causing a progressive decline in lung function ultimately resulting in reduced life span." (PMID 32192506, 2020). "Cystic fibrosis is a condition caused by mutations in the cystic fibrosis transmembrane conductance regulator (CFTR)." (PMID 32811866, 2020). "Cystic Fibrosis, an autosomal recessive genetic disease, is caused by a mutation in the gene encoding the cystic fibrosis transmembrane conductance regulator (CFTR)." (PMID 32630625, 2020). "Cystic Fibrosis is caused by mutations in the cystic fibrosis transmembrane conductance regulator (CFTR) gene, and CF patients require life-long treatment." (PMID 32443586, 2020). "Cystic fibrosis is one of the most common autosomal recessive genetic disorders among Caucasians and results from a mutation in the cystic fibrosis transmembrane conductance regulator (CFTR)." (PMID 31978131, 2020).
cystic fibrosis (continued). "Cystic fibrosis is an autosomal recessive hereditary disease caused by mutations in the Cystic Fibrosis Transmembrane Conductance Regulator (CFTR) gene." (PMID 32117250, 2020). "Again, much of the research in this field focuses on mutated CFTR and cystic fibrosis; however, even a relatively mild inflammatory setting clearly downregulates wild-type CFTR expression in the lung." (PMID 33250777, 2020). "Cystic fibrosis is an autosomal recessive disorder caused by a mutation in the CF transmembrane conductance regulator (CFTR) gene encoding the CFTR protein which regulates the movement of chloride and sodium ions across epithelial cell membranes." (PMID 33072084, 2020). "A phenotype of cystic fibrosis patients is loss of swelling response of GI epithelial cells to increased cAMP resulted from CFTR mutations." (PMID 32588198, 2020). "Cystic Fibrosis is an autosomal recessive disease originated from a mutation in the gene encoding the cystic fibrosis transmembrane conductance regulator (CFTR), a cAMP-regulated epithelial chloride channel." (PMID 33251161, 2020). "Studying water transport in the genetic disease cystic fibrosis is relevant because, mutations of the CFTR gene disrupt chloride transport at the apical membrane of epithelial cells and lead to perturbed water secretion." (PMID 32469934, 2020). "Cystic Fibrosis is caused by >2000 mutations in the CF transmembrane conductance regulator (CFTR) gene, but one mutation—F508del—occurs in ~80% of patients worldwide." (PMID 32630830, 2020). "Cystic fibrosis, the most common lethal autosomal recessive disorder among Caucasians, is caused by mutations in the CF transmembrane conductance regulator (CFTR) chloride channel gene." (PMID 33050003, 2020). "Studies show that deletion of a single amino acid in the CFTR protein causes cystic fibrosis, due to misfolding and proteasomal degradation of the CFTR protein, even though the abnormal protein still retains some function." (PMID 32759676, 2020). "More than 2000 CFTR variants have been reported to the Cystic Fibrosis Mutation Database, identified in patients with CF, a CFTR-RD or various other clinical presentations and in healthy individuals." (PMID 32512765, 2020). "There are parallels between ABCG2 141K and the important cystic fibrosis-causing gene variant, ΔF508 in CFTR, also an ABC transporter." (PMID 32164793, 2020). "Cystic fibrosis is a monogenetic disease resulting from mutations in the Cystic Fibrosis Transmembrane conductance Regulator (CFTR) gene encoding an anion channel." (PMID 33106471, 2020). "Here, we demonstrate that CRISPR/Cas9 can correct p.F508del mutation in the CFTR gene in the CFTE29o- cells and induced pluripotent stem cells (iPSCs) derived from patients with cystic fibrosis." (PMID 33175893, 2020). "Cystic fibrosis is a fatal, autosomal recessive disorder caused by mutations in the cystic fibrosis transmembrane conductance regulator (CFTR) gene." (PMID 32520327, 2020). "Other common reason for male infertility is cystic fibrosis, i.e., a recessive disease with a frequency of occurrence of 1/2500 live births, is caused by mutations in the CFTR gene on chromosome 7." (PMID 32722328, 2020). "Cystic fibrosis is a monogenic disease implicating mutations of both copies of the gene coding the cystic fibrosis transmembrane conductance regulator (CFTR) protein, thus inherited in an autosomal recessive manner." (PMID 32403302, 2020). "Cystic fibrosis is an autosomal recessive inherited disease that is caused by a dysfunction of the cystic fibrosis transmembrane conductance regulator (CFTR)." (PMID 32198528, 2020). "Cystic fibrosis, caused by mutation in Cystic Fibrosis Transmembrane Regulator (CFTR) gene, is one of the most common autosomal recessive lethal inherited diseases in the Caucasian poulation." (PMID 32439937, 2020).
cystic fibrosis (continued). "Cystic fibrosis, which primarily targets the respiratory system, is one of the most common recessively inherited disorder caused by the deficient CFTR gene that encodes a chloride channel." (PMID 32286221, 2020). "Small molecule interventions targeting the basic defect(s) caused by CFTR mutations have transformed the therapeutic landscape for Cystic Fibrosis." (PMID 32414100, 2020). "CFTR mutations cause cystic fibrosis, in which defective electrolyte and fluid transport can cause heterogeneous phenotypes of disease in different organs." (PMID 32046116, 2020). "An example is cystic fibrosis, an inherited disease caused by mutations that impair the function of CFTR, a Cl− channel important in respiratory as well as intestinal fluid secretion." (PMID 32722648, 2020). "Remarkably, a similar therapeutic strategy underlies the cystic fibrosis treatment by Lumacaftor® that increases surface expression of mutated CFTR channels." (PMID 32317970, 2020). "Loss‐of‐function mutations in CFTR cause the dehydrated secretions characteristic of the genetic disease cystic fibrosis." (PMID 33113586, 2020). "Cystic Fibrosis is a chronic autosomal recessive disease caused by defects in the cystic fibrosis transmembrane conductance regulator gene (CFTR)." (PMID 32718005, 2020). "Inflammation-related progressive lung destruction is the leading causes of premature death in cystic fibrosis, a genetic disorder caused by a defective cystic fibrosis transmembrane conductance regulator (CFTR)." (PMID 32849617, 2020). "It has recently been reported that antisense oligonucleotides designed to interfere with SMG1 can inhibit NMD restoring CFTR protein synthesis in a model of cystic fibrosis carrying the W1282X nonsense mutation in vitro." (PMID 32630050, 2020). "Mutations in the gene encoding CFTR cause the multiorgan disease Cystic Fibrosis, the most lethal recessive genetic inherited disorder in the Caucasian population." (PMID 32326361, 2020). "The most common CFTR mutation associated with cystic fibrosis is Phe508del (c.1521_1523delCTT, DF508)." (PMID 32630227, 2020). "Cystic fibrosis, which affects approximately 80,000 people worldwide, is caused by mutations in the CFTR gene which result in defects in protein quantity, biosynthetic processing, stability, regulation and/or channel gating." (PMID 33167369, 2020). "Cystic Fibrosis, caused by mutations affecting the CFTR gene, is characterised by viscid secretions in multiple organ systems." (PMID 33031374, 2020). "Cystic fibrosis is a genetic disease caused by mutations in the CF transmembrane conductance regulator (CFTR) gene, resulting in chronic bacterial lung infections and tissue damage." (PMID 32616918, 2020). "In particular, VX-809, sildenafil citrate and ibuprofen have been successfully used to rescue the misfolded F508del-CFTR mutant causing a common form of cystic fibrosis." (PMID 33009446, 2020). "Biallelic inactivating germline mutations in the CFTR gene found on chromosome 7 cause the inherited life-threatening disease cystic fibrosis, the most common autosomal recessive disease among people of European (primarily northern Europe) ancestry." (PMID 32326161, 2020). "A recent study has used base editor to correct CFTR nonsense mutations in organoid of cystic fibrosis patients." (PMID 32332735, 2020). "Cystic fibrosis is a life-shortening genetic disorder caused by mutations in the cystic fibrosis transmembrane conductance regulator (CFTR) gene." (PMID 32825766, 2020). "Thirty years have passed since cystic fibrosis transmembrane conductance regulator (CFTR) was identified as the cystic fibrosis causative gene in 1989, and the molecular mechanism of CFTR expression and dysfunction due to a genetic mutation is being clarified." (PMID 32331485, 2020). "Cystic fibrosis is a life-threatening autosomal recessivedisease, caused by mutations in the CF transmembrane conductance regulator(CFTR) chloride channel." (PMID 32946228, 2020).
cystic fibrosis (continued). "Cystic fibrosis, another example of a genetic disorder, is caused by mutations in the cystic fibrosis transmembrane conductance regulator (CFTR) protein, which is a chloride ion channel expressed on the epithelial cells of the lung, pancreas, and other organs." (PMID 32754041, 2020). "Mutations in this membrane protein cause cystic fibrosis and mutated CFTR is a target for several ERAD associated E3 ligases." (PMID 32731622, 2020). "Cystic Fibrosis, an autosomal-recessive genetic disorder, causes chronic changes including inflammation of the lungs and other organs due to the defect in the cystic fibrosis transmembrane conductance regulator (CFTR)." (PMID 33520993, 2020). "Although rare, the SAE ionocytes highly express CFTR, the gene causative of cystic fibrosis if mutated." (PMID 32727470, 2020). "In order to document the highly variable variant distribution and frequency among populations, a systematic search in PubMed was made using keywords “CFTR”, “cystic fibrosis”, “variant” or “CFTR”, “cystic fibrosis” and “mutation”." (PMID 32512765, 2020). "Cystic Fibrosis is a lethal monogenic autosomal recessive disease linked to mutations in Cystic Fibrosis Transmembrane Conductance Regulator (CFTR) protein." (PMID 32650630, 2020). "Cystic fibrosis is caused by mutations in the gene encoding the transmembrane conductance regulator (CFTR) protein." (PMID 32640650, 2020). "Mutations in these genes are associated with diseases, including cystic fibrosis (ABCC7/CFTR), Tangier disease (ABCA1/CERP), Dubin–Johnson syndrome [ABCC2/multidrug resistance‐associated protein (MRP2)] and gout [ABCG2/breast cancer resistance protein (BCRP)]." (PMID 33128234, 2020). "Cystic fibrosis is a recessive genetic disease caused by mutations in the Cystic Fibrosis Transmembrane Regulator (CFTR) gene, which codes for an anion channel involved in the conduction of both, chloride and bicarbonate ions." (PMID 32414100, 2020). "Mutations in the cystic fibrosis transmembrane conductance regulator (CFTR) channel cause cystic fibrosis." (PMID 32144307, 2020). "Cystic fibrosis is an autosomal recessive disorder caused by mutations in the CF transmembrane conductance regulator (CFTR) gene, encoding an anion channel that conducts chloride and bicarbonate across epithelial membranes." (PMID 32520327, 2020). "Like ionocytes in mouse airways and human LAE, the human SAE ionocytes highly expressed the transcription factors FOXI1 and ASCL3, V-ATPase-subunit genes (ATP6V1G3, ATP6V0B), and the Cl− ion channel CFTR, that when mutated, causes cystic fibrosis." (PMID 32727470, 2020). "Cystic fibrosis is an autosomal recessive disease due to mutations in the gene encoding CFTR and characterized by alterations in the composition and volume of secreted luminal fluids." (PMID 32676036, 2020). "Cystic fibrosis is a life limiting disease due to mutations in the cystic fibrosis conductance gene regulator (CFTR)." (PMID 32927759, 2020). "Cystic fibrosis is a common genetic malady caused by defects in the cystic fibrosis transmembrane conductance regulator (CFTR) gene and causes malfunctions in multiple organs including the GI tract." (PMID 32588198, 2020). "Cystic fibrosis, the most frequent recessive hereditary autosomal disease in the Caucasian population, is caused by mutations in the cystic fibrosis transmembrane conductance regulator (CFTR) gene." (PMID 33297418, 2020). "The first application of the CRISPR/Cas9 technique to the organoid system demonstrated correction of the mutated CFTR gene in intestinal organoids derived from cystic fibrosis patients." (PMID 30704043, 2019). "Airway mucus obstruction is the main cause of morbidity in cystic fibrosis, a disease caused by mutations in the CFTR Cl− channel." (PMID 31732694, 2019). "Cystic fibrosis is a multisystem genetic disease caused by mutations in the cystic fibrosis conductance regulator (CFTR) gene." (PMID 31664087, 2019).
cystic fibrosis (continued). "Cystic fibrosis is an autosomal recessive disease, due to the occurrence of cystic fibrosis transmembrane conductance regulator (CFTR) gene mutations and it is characterized by a variable cytokines pro-inflammatory milieu." (PMID 31412612, 2019). "Cystic fibrosis is a common autosomal recessive disease caused by mutations in the cystic fibrosis transmembrane conductance regulator (CFTR) gene, which encodes an anion channel." (PMID 30875857, 2019). "Infection by rapidly growing Mycobacterium abscessus is increasingly prevalent in cystic fibrosis, a genetic disease caused by a defective CF transmembrane conductance regulator (CFTR)." (PMID 30759393, 2019). "Cystic fibrosis is a life-threatening, recessive genetic disease caused by mutations in a gene on chromosome 7 encoding for the CFTR protein." (PMID 31143125, 2019). "Cystic fibrosis is one of the most common genetic disorders, that is resulted by the mutation of the gene encoding the CF transmembrane conductance regulator (CFTR) protein." (PMID 30894846, 2019). "Cystic Fibrosis is caused by mutations in the CFTR anion channel, many of which cause its misfolding and degradation." (PMID 31408507, 2019). "CFTR is the chloride channel mutated in cystic fibrosis, and loss of CFTR function leads to progressive decreases in lung function, pancreatic exocrine dysfunction, and intestinal obstruction or constipation." (PMID 30975131, 2019). "The tight correlation between folding and function in cystic fibrosis patients with CFTR mutations of the altered-conductance CFTR class provides an attractive paradigm for characterizing mode of action of novel therapeutics." (PMID 30659068, 2019). "Loss-of-function mutations in the Cystic Fibrosis Transmembrane conductance Regulator (CFTR) channel in human airway epithelial cells are responsible for Cystic Fibrosis." (PMID 31551433, 2019). "The spectrum and frequencies of CFTR mutations causing Cystic fibrosis varies among different populations in Europe, and beyond." (PMID 31245908, 2019). "Over 2,000 CFTR gene variants have been reported in the Cystic Fibrosis Mutation Database (CFTR1 Database)." (PMID 32153386, 2019). "An improved understanding of the cystic fibrosis transmembrane conductance regulator (CFTR) protein structure and the consequences of CFTR gene mutations have allowed the development of novel therapies targeting specific defects underlying CF." (PMID 30873022, 2019). "Cystic fibrosis is a genetic disorder caused by mutations in the Cystic Fibrosis Transmembrane Conductance Regulator gene (CFTR), leading to viscous secretions accumulating on epithelial surfaces in both the lungs and the gastrointestinal tract." (PMID 31083321, 2019). "Cystic fibrosis is an autosomal recessive disease characterized by a defect in the cystic fibrosis transmembrane conductance regulator (CFTR) gene on chromosome 7, which encodes for a chloride ion transporter on the apical membrane of epithelial cells." (PMID 30959944, 2019). "Cystic fibrosis is caused by a mutation in CFTR, an anion channel and member of the ABC-transporter family." (PMID 30659068, 2019). "Cystic fibrosis is a genetic disease caused by mutations of the gene encoding for the cystic fibrosis transmembrane conductance regulator (CFTR), which results in reduced protein function." (PMID 31195689, 2019). "Deletion of phenylalanine 508 (F508del) in the cystic fibrosis transmembrane conductance regulator (CFTR) anion channel is the most frequent mutation causing cystic fibrosis." (PMID 31311979, 2019). "Cystic fibrosis is an autosomal recessive condition caused by mutations in the CF transmembrane conductance regulator (CFTR) gene, which encodes a cAMP activated chloride channel of the same name." (PMID 31375720, 2019). "Cystic fibrosis is a genetic autosomal recessive disease commonly seen in Caucasians and is resulted from mutations in CFTR gene, which leads to chronic inflammation and recurrent and chronic bacterial infections." (PMID 32010692, 2019).